SPAG11A (sperm associated antigen 11A)
Description:
Has antimicrobial activity against E.coli (By similarity). Plays a role in the defense response in the male reproductive tract, contributing to sperm maturation, storage and protection (By similarity).
Synonyms: He2; EDDM2A
Tractability: Antibody: UniProt places it where antibodies can reach, with high confidence; UniProt predicts a signal peptide or a membrane-spanning region; its Gene Ontology location is reachable by antibodies, with medium confidence.
Gene: Protein-coding gene on chromosome 8 (7,847,876 to 7,868,867, forward strand). Ensembl gene ENSG00000178287.
Subcellular location: Secreted
Subcellular location (Human Protein Atlas): Golgi apparatus; Predicted to be secreted
Gene Ontology:
Cellular component: extracellular region
Genetic constraint (gnomAD): Loss-of-function variants: 2 observed, 1.55 expected, observed/expected ratio (o/e) 1.29, 90% interval 0.43 to 1.91. That is too few expected variants to judge how well the gene tolerates losing a copy. Missense variants: 21 observed, 26.73 expected, observed/expected ratio (o/e) 0.79, 90% interval 0.56 to 1.13. Synonymous variants: 8 observed, 7.02 expected, observed/expected ratio (o/e) 1.14, 90% interval 0.66 to 1.83.
Homologues: Orthologues: chimpanzee SPAG11B (59% identical), macaque SPAG11B (48% identical), mouse Spag11b (35% identical), dog SPAG11B (34% identical). Paralogues in human: SPAG11B (98% identical).
Diseases named in the same sentence as SPAG11A in open-access papers:
SPAG11A is named in the same sentence as 6 diseases in open-access papers, as found by Europe PMC text mining. Sharing a sentence is not in itself a finding about the gene and the disease. The quoted sentences say what the papers report.
infertile (1 paper, 2024). "The aim of this study was to evaluatethe expression level of the SPAG11A gene and spermparameters in infertile men with grade 1 and 2 varicocele before and aftertreatment." (PMID 38446746, 2024). "The mean age of infertile men with varicocele and normal subjects was31.3±6.25 and 27.5±2.95, respectively (p=0.099).The expression levels of the SPAG11A gene were analyzed byquantitative RT-PCR in the infertile men with varicocele before and aftertreatment, as well as in healthy control subjects." (PMID 38446746, 2024).
varicocele (1 paper, 2024). A condition characterized by the dilated tortuous veins of the spermatic cord with a marked left-sided predominance. "In the present study, we found that SPAG11A mRNA levels were lowerin patients with varicocele than in healthy controls, and these levels showedstatistically significant differences between the pre-treatment group and controls(p=0.007)." (PMID 38446746, 2024). "However, there was a slightincrease in SPAG11A expression and sperm normalmorphology following varicocele repair." (PMID 38446746, 2024). "SPAG11A gene expression and semen parameters may be affectedby varicocele." (PMID 38446746, 2024).
tumor (1 paper, 2019). "A prognostic signature based on RGs (AGTR1, CTGF, FAM3B, IL11, IL17C, PTH2R and SPAG11A) performed moderately in prognostic predictions and correlated with age, tumor stage, metastasis, number of lesions, and tumor burden." (PMID 30661062, 2019).
SPAG11A also shares sentences with these, for which no sentence is quoted: centronuclear myopathy (1 paper); infection (1); papillary thyroid cancer (1).